MARVELD1 (MARVEL domain containing 1)
Description:
Microtubule-associated protein that exhibits cell cycle-dependent localization and can inhibit cell proliferation and migration.
Synonyms: MRVLDC1; MGC4415; GB14; FLJ23440; FLJ22343; bA548K23.8; MARVD1
Tractability: Antibody: UniProt places it where antibodies can reach, with medium confidence; UniProt predicts a signal peptide or a membrane-spanning region; its Gene Ontology location is reachable by antibodies, with medium confidence.
Gene: Protein-coding gene on chromosome 10 (97,713,173 to 97,718,150, forward strand). Ensembl gene ENSG00000155254.
Subcellular location: Cell membrane; Cytoplasm, cytoskeleton; Nucleus
Gene Ontology:
Molecular function: structural constituent of myelin sheath
Biological process: myelination
Cellular component: membrane; cytoskeleton; nucleus; plasma membrane
Genetic constraint (gnomAD): Loss-of-function variants: 6 observed, 11.1 expected, observed/expected ratio (o/e) 0.54, 90% interval 0.29 to 1.07. The upper end of that interval is the gene's LOEUF score, 1.07, which puts it in group 4 of 6, group 1 being the genes least tolerant of losing a copy. Missense variants: 195 observed, 225.75 expected, observed/expected ratio (o/e) 0.86, 90% interval 0.77 to 0.97. Synonymous variants: 107 observed, 111.68 expected, observed/expected ratio (o/e) 0.96, 90% interval 0.82 to 1.12.
Homologues: Orthologues: chimpanzee MARVELD1 (100% identical), macaque MARVELD1 (99% identical), guinea pig MARVELD1 (92% identical), rabbit MARVELD1 (92% identical), mouse Marveld1 (88% identical), pig MARVELD1 (88% identical), rat Marveld1 (88% identical), dog MARVELD1 (87% identical), tropical clawed frog marveld1 (46% identical), zebrafish marveld1 (43% identical), Caenorhabditis elegans F28H1.4 (13% identical), Caenorhabditis elegans F47B3.3 (10% identical). Paralogues in human: PLLP (23% identical), CMTM3 (20% identical), CMTM6 (18% identical), PLP2 (18% identical), CMTM4 (17% identical), MAL (17% identical), CMTM8 (17% identical), MALL (16% identical), MAL2 (16% identical), CMTM5 (13% identical), CMTM7 (12% identical), CMTM1 (11% identical), and 2 more.
Diseases named in the same sentence as MARVELD1 in open-access papers:
MARVELD1 is named in the same sentence as 33 diseases in open-access papers, as found by Europe PMC text mining. Sharing a sentence is not in itself a finding about the gene and the disease. The quoted sentences say what the papers report.
colorectal cancer (3 papers, 2023 to 2025). A primary or metastatic malignant neoplasm that affects the colon or rectum. "Moreover, acetylation enhances the interaction of PARP1 with MARVELD1, promoting genomic stability in colorectal cancer cells post-DNA damage." (PMID 39528473, 2024). "In colorectal cancer, PARP1 interacts with MARVELD1 to form a positive feedback loop → stabilizes PARP1 and ↑NAA50‐mediated acetylation → enhances genomic stability and chemoresistance." (PMID 40904702, 2025). "In colorectal cancer (CRC), MARVEL domain‐containing protein 1 (MARVELD1) mediates DNA damage response to maintain genome stability." (PMID 40904702, 2025). "Moreover, MARVELD1 partnering with PARP1 facilitates resistance to genotoxic drugs and disrupts PARP inhibitor (PARPi) effect in PDX model of colorectal cancer (CRC)." (PMID 36750717, 2023). "Moreover, partnership of MARVELD1 and PARP1 promotes resistance to DNA damaging therapy in colorectal cancer (CRC)." (PMID 36750717, 2023).
hepatocellular carcinoma (3 papers, 2013 to 2022). A malignant tumor that arises from hepatocytes. "The overexpression of MARVELD1 inhibited proliferation and enhanced chemosensitivity in hepatocellular carcinoma cells." (PMID 23826386, 2013). "Previously, we showed that the expression of MARVELD1 is remarkably downregulated in multiple tumors, especially in breast cancer and hepatocellular carcinoma." (PMID 23826386, 2013). "However, it has been reported that overexpression of MARVELD1 promotes the tumor sensitivity to chemotherapy in hepatocellular carcinoma, and our results seems conflicted with previous study." (PMID 27447558, 2016). "In addition to that, previous studies have found that MARVEL domain-containing 1 (MARVELD1) could inhibit tumor cell proliferation and enhance the sensitivity to chemotherapeutic drugs in hepatocellular carcinoma." (PMID 36353110, 2022).
lung carcinoma (3 papers, 2014 to 2022). "The decreased MARVELD1 level in lung cancer reduces NMD efficiency through diminishing the association between NMD complex component UPF1/SMG1 and premature termination codons containing mRNA (PTC-mRNA)." (PMID 25520033, 2014). "Here, we found the reduced MARVELD1 expression significantly correlated with diagnostic histopathology and malignant degree of lung cancers." (PMID 25520033, 2014). "Immunohistochemical analysis and Western blotting experiments showed that the down-regulation of MARVELD1 was associated with malignant progression of lung cancer." (PMID 25520033, 2014). "In lung cancers, the expression of MARVELD1 significantly correlated with diagnostic histopathology and degree of malignancy as it was inactivated via DNA hypermethylation and histone deacetylation synergistically but suppressed the epithelial-mesenchymal transition 10-11." (PMID 34976185, 2022). "The results suggested that MARVELD1 silencing is an appealing diagnostic biomarker for lung cancer and epigenetic silencing of MARVELD1 gene links with the regulatory mechanism of NMD pathway in lung cancer, which may be required for tumorigenesis." (PMID 25520033, 2014). "MARVELD1 is synergistically inactivated through both DNA hypermethylation and histone deacetylation in lung cancer cells." (PMID 34976185, 2022). "To understand the mechanisms involved in regulation of MARVELD1 expression in lung cancer, we analyzed transcriptional regulation of MARVELD1 gene." (PMID 25520033, 2014). "In vitro, we further investigated the methylation status of MARVELD1 promoter in lung cancer cell lines by bisulfite sequencing PCR and DNA sequence analysis." (PMID 25520033, 2014). "Epigenetic silencing of MARVELD1 gene was observed in low MARVELD1-expressing lung cancer cell lines." (PMID 25520033, 2014). "In the present study, we tested the expression pattern of MARVELD1 and the epigenetic status of MARVELD1 promoter in lung cancer." (PMID 25520033, 2014). "DNA hypermethylation and histone deacetylation synergistically inactivated MARVELD1 gene in lung cancer cells." (PMID 25520033, 2014). "The reduced expression of MARVELD1 was confirmed in lung cancer data from The Cancer Genome Atlas (TCGA) dataset." (PMID 25520033, 2014). "In lung cancer cell lines, the methylation states of the CpGs in MARVELD1 promoter region were found to be hypermethylated." (PMID 25520033, 2014). "In this study, we observed that MARVELD1 is down-regulated in lung cancer tissues, especially small-cell lung cancer tissues." (PMID 25520033, 2014). "Considering the aberrant regulation of MARVELD1 gene in lung cancer, therefore, we discussed the gene silencing mechanism of MARVELD1 and the relationship between epigenetically masked MARVELD1 and NMD function in lung cancer cells." (PMID 25520033, 2014). "This study was carried out to determine the biological and clinical significance of MARVELD1 gene silencing in lung cancer." (PMID 25520033, 2014). "Interference of MARVELD1 enhances the sensitivity of lung cancer cells to gefitinib as well." (PMID 27447558, 2016). "Therefore, we investigated the influence of 5-aza-CdR on the expression of MARVELD1 gene in lung cancer cells." (PMID 25520033, 2014). "To examine whether MARVELD1 affected NMD, we generated a NMD reporter plasmid carrying a PTC derived from deletion mutation of endogenous LRP1B gene exons 1–9 in lung cancer cell QG56; GFP-coding region was inserted at C-terminal of LRP1B gene." (PMID 25520033, 2014). "In addition, we also found histone acetylation and DNA demethylation synergistically activated MARVELD1 gene in lung cancer cells." (PMID 25520033, 2014). "Thus, silencing expression of MARVELD1 has a potential to be developed as a biomarker for malignant phenotype of lung cancer." (PMID 25520033, 2014). "The observation was also confirmed in lung cancer cell line A549 expressing low level of MARVELD1." (PMID 25520033, 2014).
lung carcinoma (continued). "Taken together, these findings suggested that epigenetic inactivation of MARVELD1 gene will weaken NMD pathway in lung cancer, which may be required for lung tumorigenesis." (PMID 25520033, 2014). "In this study, we reported the correlation between MARVELD1 silencing and lung cancer." (PMID 25520033, 2014). "Remarkably, silencing of MARVELD1 expression by aberrant epigenetic modifications reduced the efficiency of NMD and represented a potential biomarker in lung cancer." (PMID 25520033, 2014). "We further detected the potential interaction between endogenous MARVELD1 and SMG1 in lung cancer cell line NCI-H292 by using Co-IP followed by western blotting analysis." (PMID 25520033, 2014). "In this study, we showed MARVELD1 co-localized and interacted with SMG1, the core kinase of the NMD machinery, in lung cancer cells." (PMID 25520033, 2014). "Therefore, we deducted that MARVELD1 silencing may be required for tumorigenesis and has a potential to be developed as a biomarker for malignant phenotype of lung cancer, which possesses considerable value in prognosis prediction, progression monitoring and treatment evaluating." (PMID 25520033, 2014). "The reduced MARVELD1 expression, due to promoter hypermethylation, attenuated NMD, which indicated aberrant mRNA surveillance mechanism in lung cancer." (PMID 25520033, 2014). "Analysis of tumor/nontumor adjacent tissue (T/N) ratios for MARVELD1 expression in 25 NSCLC patients revealed that MARVELD1 expression was decreased in 72% lung cancer tissues." (PMID 25520033, 2014). "Moreover, we constructed the NMD reporter plasmid expressing PTC-containing truncated LRP1B-GFP mRNA (LRP1B exons 1–9 from lung cancer cell line QG56), and demonstrated that MARVELD1 bound PTC-mRNA as efficient as NMD core factor UPF1 and SMG1 by RNA-ChIP based reporter system." (PMID 25520033, 2014).
colon cancer (2 papers, 2021 to 2022). "Downregulation of MARVELD1 in colon cancer was associated with both poor overall survival (OS) and progression free survival (PFS) unlike in cancers with high expression of MARVELD1." (PMID 34976185, 2022). "Low expression of MARVELD1 was significantly associated with poor prognosis of colon cancer." (PMID 34976185, 2022). "Gene Ontology enrichment analysis revealed that MARVELD1 may modulate processes associated with inhibition of tumorigenesis in colon cancer." (PMID 34976185, 2022). "All these results suggested that the role of MARVELD1 in colon cancer progression is mediated by the Wnt/β-catenin pathway." (PMID 34976185, 2022). "Colon cancer patients with low expression of MARVELD1 had worse progression free survival and overall survival than those with high expression levels in our cohort." (PMID 34976185, 2022). "Patients with low expression of MARVELD1 had poor prognosis than those with high expression levels in our colon cancer cohort." (PMID 34976185, 2022). "In colon cancer, transcription factors regulate MARVELD1 expression, and MARVELD1 in turn decreases the cellular level of β-catenin." (PMID 34976185, 2022). "LiCl significantly enhanced proliferation, migration, and invasion of colon cancer cells overexpressing MARVELD1." (PMID 34976185, 2022). "We isolated the cytoplasm and nucleus from colon cancer cells and found that overexpression of MARVELD1 inhibited the expression of β-catenin in the nucleus and in the total protein." (PMID 34976185, 2022). "In colon cancer, transcription factors regulate MARVELD1 expression, and MARVELD1 subsequently decreases the cellular level of β-catenin." (PMID 34976185, 2022). "The expression of MARVELD1 was downregulated in seven colon cancer cell lines (SW620, HT29, HCT116, LoVo, DLD-1, RKO, and SW480) compared with normal colon cells, NCM460, at both mRNA and protein levels." (PMID 34976185, 2022). "In the colon cancer group, there were 60 and 36 patients with low and high expression of MARVELD1, respectively." (PMID 34976185, 2022). "With Wnt/β-catenin activator LiCl treatment, rescue experiments demonstrated that the role of MARVELD1 in colon cancer progression was dependent on the Wnt/β-catenin pathway." (PMID 34976185, 2022). "In this study, MARVELD1 inhibited cell proliferation, migration, and invasion in vitro and inhibited proliferation in vivo in colon cancer cells." (PMID 34976185, 2022). "In our cohort of patients with colon cancer, low expression of MARVELD1 indicated poor prognosis." (PMID 34976185, 2022). "The function of MARVELD1 in colon cancer remains to be studied." (PMID 34976185, 2022). "We will verify 13 methylation sites of the MARVELD1 promoter locus in future colon cancer studies." (PMID 34976185, 2022). "To examine whether the function of MARVELD1 in colon cancer was mediated by the Wnt/β-catenin pathway, we used LiCl to activate the Wnt/β-catenin pathway in a rescue experiment." (PMID 34976185, 2022). "Therefore, we aimed to elucidate the downstream regulatory functions of MARVELD1 and the correlation among MARVELD1 and key genes of important pathways in colon cancer." (PMID 34976185, 2022). "MARVELD1 also inhibited the proliferation, migration, and invasion of colon cancer cells." (PMID 34976185, 2022). "MARVELD1 is highly expressed in colon cancer and male germ cell tumor, hinting that the role of MARVELD1 in cancer may be a double-edged sword." (PMID 34008750, 2021). "Therefore, MARVELD1 acts as a tumor suppressor and inhibits tumor growth in colon cancer." (PMID 34976185, 2022). "However, the function of MARVELD1 in colon cancer is unknown." (PMID 34976185, 2022). "Fourth, we revealed that MARVELD1 regulated the occurrence and progression of tumors by inhibiting WNT/β-catenin signaling in colon cancer." (PMID 34976185, 2022).
colon cancer (continued). "As the main functions and important pathways modulated via MARVELD1 were found in colon cancer when analyzed through GO and KEGG, colon cancer was selected for functional studies to elucidate the potential role of MARVELD1 in inhibiting tumorigenesis." (PMID 34976185, 2022). "Third, we elucidated the downstream regulatory functions of MARVELD1, the correlation between MARVELD1 and key genes of important pathways through GO and KEGG analysis in colon cancer." (PMID 34976185, 2022). "The expression of MARVELD1 was lower in colon cancer tissues than in their non-cancer tissue counterparts." (PMID 34976185, 2022). "Moreover, in our cohort, the expression of MARVELD1 was lower in colon cancer samples than in their corresponding non-cancer counterparts." (PMID 34976185, 2022).
glioma (2 papers, 2021 to 2023). A benign or malignant brain and spinal cord tumor that arises from glial cells (astrocytes, oligodendrocytes, ependymal cells). "Next, GSEA analysis was performed to discern the possible MARVELD1-associated pathways in glioma." (PMID 34008750, 2021). "In this paper, MARVELD1 was up-regulated in glioma and associated with poor outcomes and grade." (PMID 34008750, 2021). "MARVELD1 expression positively correlated with chemotherapy resistance in ovarian cancer and a poor prognosis in gliomas, and it was regarded as the genomic instability-derived gene prognostic signature." (PMID 36750717, 2023). "Since JAK/STAT signaling pathway is a key molecule involved in tumor cell proliferation, invasion, and migration, we believed that MARVELD1 functions in glioma at least partially through JAK/STAT signaling pathway." (PMID 34008750, 2021). "MARVELD1 was expressed at high levels in glioma and high MARVELD1 expression was related to prognosis and WHO grade (range I-IV)." (PMID 34008750, 2021). "Kaplan-Meier survival analysis revealed that the higher MARVELD1 expression, the shorter the survival time of patients with glioma." (PMID 34008750, 2021). "In this present work, we found for the first time that MARVELD1 was up-regulated in glioma, and patients with high expression of MARVELD1 presented a shorter survival time." (PMID 34008750, 2021). "This work aimed to research the function of MARVEL domain-containing protein 1 (MARVELD1) in glioma as well as its functioning mode." (PMID 34008750, 2021). "MARVELD1 contributed to promoting the malignant progression of glioma, which is the key driver of activation of JAK/STAT signaling pathway in gliomas." (PMID 34008750, 2021). "Here, patients with WHO IV glioma presented higher MARVELD1 expression compared with WHO II and WHO III gliomas, and higher MARVELD1 expression resulted in shorter survival time." (PMID 34008750, 2021). "Based on the data in the TCGA and GTEx databases, we found that MARVELD1 expression was markedly enhanced in glioma tissues compared to that in the normal control." (PMID 34008750, 2021). "Cell Counting Kit-8 (CCK-8), colony formation, and Transwell assays were carried out to determine the impact of MARVELD1 on malignant biological behavior of glioma, such as proliferation, invasion, and migration." (PMID 34008750, 2021). "Considering that MARVELD1 enhanced the proliferation of glioma cells, we next performed the Transwell assay to evaluate the potential function of MARVELD1 in the invasive and migratory abilities of glioma cells." (PMID 34008750, 2021). "Then, to identify the expression of MARVELD1 in glioma cell lines U87 and U251, qRT-PCR was performed." (PMID 34008750, 2021). "MARVELD1 was expressed at high levels in glioma tissues and cell lines." (PMID 34008750, 2021). "How the function of MARVELD1 in glioma is realized needs further study." (PMID 34008750, 2021). "Also, based on the bio-functional assays, MARVELD1 promoted the malignant phenotype of glioma cells." (PMID 34008750, 2021). "All these findings indicated that MARVELD1 was involved in the malignant progression of glioma." (PMID 34008750, 2021). "MARVELD1 promoted the invasion and migration of glioma cells." (PMID 34008750, 2021). "All these data showed that the promoting impact of MARVELD1 on the malignant progression of glioma may be achieved via JAK/STAT signaling pathway." (PMID 34008750, 2021). "Kaplan Meier plots revealed that high MARVELD1 expression in glioma was related to poor outcomes." (PMID 34008750, 2021). "Bioinformatics analysis was utilized to assess the MARVELD1 expression in glioma tissues and its relationship with grade and prognosis, based on The Cancer Genome Atlas (TCGA), Genotype-Tissue Expression (GTEx), and Chinese Glioma Genome Atlas (CGGA) databases." (PMID 34008750, 2021). "JAK/STAT pathway mediates the modulation of MARVELD1 on the biological behavior of glioma cells." (PMID 34008750, 2021).
glioma (continued). "Also, we found that MARVELD1 was correlated to grade, and the level of MARVELD1 in patients with high-grade glioma was higher than that in patients with low-grade glioma." (PMID 34008750, 2021). "Finally, we found that JAK/STAT signaling pathway mediated the function of MARVELD1 in glioma." (PMID 34008750, 2021). "Additionally, up-regulation of MARVELD1 contributed to accelerating the malignant biological behavior of glioma cells, such as proliferation, invasion, and migration, and this function may be achieved through JAK/STAT pathway." (PMID 34008750, 2021). "Herein, we assessed the MARVELD1 function in the malignant biological behavior of glioma cells as well as whether JAK/STAT pathway mediates this function, hoping to afford an effective biomarker for the clinical treatment of glioma." (PMID 34008750, 2021).
liver cancer (2 papers, 2021 to 2022). An epithelial or non-epithelial malignant neoplasm that arises from the liver. "Previously, MARVELD1 has been studied for its anti-cancer effect, for instance, MARVELD1 inhibits the proliferation of malignant cells in liver cancer as well as suppresses EMT in non-small cell lung cancer." (PMID 34008750, 2021).